NLE1 (notchless homolog 1)
Description:
Plays a role in regulating Notch activity. Plays a role in regulating the expression of CDKN1A and several members of the Wnt pathway, probably via its effects on Notch activity. Required during embryogenesis for inner mass cell survival (By similarity).
Synonyms: FLJ10458; Rsa4; HUSSY7; NLE
Tractability: Small molecule: a structure with a bound ligand is known. PROTAC: ubiquitination databases record sites on it; its protein half-life has been measured.
Gene: Protein-coding gene on chromosome 17 (35,128,730 to 35,142,306, reverse strand). Ensembl gene ENSG00000073536.
Subcellular location: Nucleus, nucleolus
Subcellular location (Human Protein Atlas): Nucleoli; Nucleoplasm
Gene Ontology:
Molecular function: protein binding
Biological process: regulation of Notch signaling pathway
Cellular component: nucleolus
Genetic constraint (gnomAD): Loss-of-function variants: 36 observed, 61.44 expected, observed/expected ratio (o/e) 0.59, 90% interval 0.45 to 0.77. The upper end of that interval is the gene's LOEUF score, 0.77, which puts it in group 3 of 6, group 1 being the genes least tolerant of losing a copy. Missense variants: 551 observed, 653.44 expected, observed/expected ratio (o/e) 0.84, 90% interval 0.79 to 0.9. Synonymous variants: 242 observed, 261.19 expected, observed/expected ratio (o/e) 0.93, 90% interval 0.83 to 1.03.
Homologues: Orthologues: chimpanzee NLE1 (99% identical), macaque NLE1 (98% identical), pig NLE1 (96% identical), rabbit NLE1 (94% identical), mouse Nle1 (94% identical), rat Nle1 (94% identical), guinea pig NLE1 (93% identical), dog NLE1 (90% identical), tropical clawed frog nle1 (80% identical), zebrafish nle1 (75% identical), Drosophila melanogaster Nle (57% identical), Caenorhabditis elegans gldi-1 (56% identical).
Diseases named in the same sentence as NLE1 in open-access papers:
NLE1 is named in the same sentence as 11 diseases in open-access papers, as found by Europe PMC text mining. Sharing a sentence is not in itself a finding about the gene and the disease. The quoted sentences say what the papers report.
colon cancer (2 papers, 2022 to 2025). "Up-regulation of the NLE1 mRNA in colon cancer cells promotes cell migration and invasion of colon cancer cells and inhibits the apoptosis ability of colon cancer cells." (PMID 41373732, 2025).
malignant melanoma (2 papers, 2022 to 2025). "In contrast to the positive prognostic impact of these genes in combination with TGFB2, NLE1 is elevated and positively correlated with tumor stage and metastasis in melanoma." (PMID 41373732, 2025). "Only few studies concerning malignant melanoma and colon adenocarcinoma indicated that NLE1 may have certain potential in the regulation of tumor growth and prediction of patients’ prognosis." (PMID 36818671, 2022). "carried out a more detailed study and demonstrated that NLE1 could promote the development of malignant melanoma through promoting cell proliferation, cell migration and inhibiting cell apoptosis, indicating the role of NLE1 in melanoma development." (PMID 36818671, 2022).
non-small cell lung carcinoma (2 papers, 2022 to 2025). A group of at least three distinct histological types of lung cancer, including non-small cell squamous cell carcinoma, adenocarcinoma, and large cell carcinoma. "NLE1 has also been implicated in the progression of non-small-cell lung cancer." (PMID 41373732, 2025). "Expression patterns of NLE1 in non-small cell lung cancer tissues and para-carcinoma tissues revealed in immunohistochemistry analysis." (PMID 36818671, 2022). "Relationship between NLE1 expression and tumor characteristics in patients with non-small cell lung cancer." (PMID 36818671, 2022).
brain tumor (1 paper, 2025). "Interestingly, previous studies have reported that NLE1 is a critical regulator of brain tumor stem cell growth and survival in GBM." (PMID 41020875, 2025).
breast carcinoma (1 paper, 2025). "For TGFB2-dependent biomarkers, elevated TGFB2 mRNA expression is a prognostic biomarker associated with breast cancer patients that is correlated with improved OS outcomes at high expression levels of GDAP1, TBL1XR1, RNFT1, HACL1, SLC27A2, NLE1, and TXNDC16." (PMID 41373732, 2025). "In cases dependent on TGFB2, increased mRNA expression of TGFB2 alongside higher levels of GDAP1, TBL1XR1, RNFT1, HACL1, SLC27A2, NLE1, or TXNDC16 was correlated with improved OS among breast cancer patients, of which four genes were upregulated in tumor tissues (SLC27A2, TXNDC16, TBL1XR1, GDAP1)." (PMID 41373732, 2025).
chronic kidney disease (1 paper, 2023). Impairment of the renal function secondary to chronic kidney damage persisting for three or more months. "The other interesting alternatively spliced genes were engaged in chemical carcinogenesis (ARAF), chronic kidney disease (NEK8) and kidney development (CNTRL, TET2, NLE1)." (PMID 38074096, 2023).
lung carcinoma (1 paper, 2022). "First of all, the expression of NLE1 in lung cancer tissues and para-carcinoma tissues was investigated and statistically analyzed in a combination of tumor characteristics and patients’ survival." (PMID 36818671, 2022). "Herein, through detecting NLE1 expression in lung cancer tissues and para-carcinoma tissues, upregulation of NLE1 in lung cancer was revealed." (PMID 36818671, 2022). "Correspondingly, we also showed the involvement of Akt pathway in NLE1-induced regulation of lung cancer cell phenotypes." (PMID 36818671, 2022). "Despite of these, the mechanistic study in our study identified CDK1 as a potential downstream target of NLE1 in the regulation of lung cancer." (PMID 36818671, 2022). "In conclusion, this study identified NLE1 as a critical regulator of lung cancer, which is upregulated in lung cancer and plays a vital role in the regulation of cell phenotypes." (PMID 36818671, 2022). "Further statistical analysis showed that elevation of NLE1 expression was positively correlated with pathological stage of tumor and negatively correlated with survival of patients, indicating the potential tumor-promoting role of NLE1 in lung cancer." (PMID 36818671, 2022). "In our future work, whether NLE1 regulates lung cancer through Notch1 signaling and the molecular regulatory mechanism between NLE1 and CDK1 would be further explored and investigated." (PMID 36818671, 2022). "Moreover, mechanistic study clarifies that the regulation of lung cancer by NLE1 needs the participation of CDK1 as a downstream target, whose E2F1-mediated transcription was regulated by NLE1." (PMID 36818671, 2022). "Therefore, NLE1 may act as a prognostic indicator and therapeutic target of lung cancer." (PMID 36818671, 2022). "In this study, except for the regulatory effects of CDK1 itself, we also found that knockdown of CDK1 could partially eliminate the promotion effects of lung cancer induced by NLE1 overexpression, suggesting CDK1 as an essential link in the function of NLE1 in lung cancer." (PMID 36818671, 2022).
tumor (3 papers, 2022 to 2025). "NLE1 expression is significantly higher in tumor tissues than in normal tissues, is correlated with the pathological stage, and can be considered a tumor promoter." (PMID 41373732, 2025). "Strikingly, the depletion of NLE1 contributed to significant diminishment of fluorescence intensity (P < 0.01) as well as inhibition of tumor growth." (PMID 36818671, 2022). "High NLE1 expression was observed in 56.2% tumor specimens (41/73), while among 71 non-tumor samples, tissues harboring low NLE1 levels accounted for the majority (60/71) (P < 0.001)." (PMID 36818671, 2022). "Having shown that NLE1 depletion displayed potent suppressive effects in vitro, we further assessed the influence of NLE1 on tumor growth in vivo." (PMID 36818671, 2022). "In fact, although few, the role of NLE1 in the development and progression of tumor development has been studied to some extent." (PMID 36818671, 2022). "To clarify the underlying role of NLE1 in NSCLC development, we performed IHC analysis of a tissue microarray containing 73 NSCLC specimens and 71 non-tumor samples." (PMID 36818671, 2022). "We thus subcutaneously injected NLE1-deficient A549 cells into four-week-old BALB-c nude mice, and measured tumor growth indicators (GFP label on lentivirus vector) before sacrifice of animal." (PMID 36818671, 2022). "Furthermore, in colorectal cancer, the ribosomal biogenesis factor NLE1 plays a key role in tumour growth and progression." (PMID 37685308, 2023). "In conclusion, this study identified NLE1 as a novel tumor promotor in the development and progression of NSCLC, which may be a potential therapeutic target in the treatment of NSCLC." (PMID 36818671, 2022). "Obviously, NLE1 inhibition was capable of decreasing tumor weight (P < 0.05)." (PMID 36818671, 2022). "Therefore, our study demonstrated the tumor-promoting role of NLE1 in NSCLC which may be mediated by CDK1." (PMID 36818671, 2022). "As for the mechanism, it was demonstrated that NLE1 may execute its tumor-regulating function through activating E2F1-mediated transcription of CDK1, and PI3K/Akt signaling pathway was also supposed as a downstream of NLE1 in the regulation of NSCLC." (PMID 36818671, 2022). "The outcomes showed that NLE1 expression is significantly higher in tumor tissues than normal tissues, and is correlated with the pathological stage." (PMID 36818671, 2022). "In the absence of SMAD4, the TGF-β signalling pathway-mediated downregulation of NLE1 is prevented by the ectopic expression of c-MYC, which occupies the E-box-containing region within the NLE1 promoter and upregulates NLE1, thereby promoting tumour progression." (PMID 37685308, 2023). "Three genes (NLE1, HACL, and RNFT1) did not exhibit significant upregulation in tumor tissues." (PMID 41373732, 2025).
cancer (2 papers, 2019 to 2022). A tumor composed of atypical neoplastic, often pleomorphic cells that invade other tissues. "Actually, current results showed that NLE1 presented similar functions with Notch1 in the regulation of human cancer." (PMID 36818671, 2022). "However, although the role of Notch signaling pathway in cancer has been comprehensively investigated, the relationship between human cancer and NLE1 was rarely reported and mains largely unknown." (PMID 36818671, 2022). "Therefore, it was fairly reasonable to deduce that NLE1 may also play some regulatory roles in the development of human cancer." (PMID 36818671, 2022). "More importantly, CDK1 is a well-known cancer-promoting factor in NSCLC, implying CDK1 as a potential downstream of NLE1." (PMID 36818671, 2022). "In the end, CCT6A, UTP18, YRDC, RRP12, RFT1, NLE1, and DDOST were essential genes across pan-cancer including COAD cells." (PMID 31867042, 2019). "Dependency score analysis by DepMap showed that ACTG1 and RHOQ were less essential across pan-cancer cells including COAD cell lines, and CCT6A, UTP18, YRDC, RRP12, RFT1, NLE1, as well as DDOST were essential across pan-cancer cells including most of COAD cell lines." (PMID 31867042, 2019). "In addition, CCT6A, UTP18, YRDC, RRP12, RFT1, NLE1, as well as DDOST were essential genes across pan-cancer including COAD cells, and ACTG1 and RHOQ were less essential genes in cancer cells." (PMID 31867042, 2019).
Muscular Disorders (1 paper, 2022). "Regarding their regulatory function, the functional network “Neurological Disease, Skeletal and Muscular Disorders, Cell-To-Cell Signaling and Interaction” seems to be the target of these two miRNAs, with NHPH3 and NLE1 being the two most significantly predicted common targets of the two miRNAs." (PMID 35602517, 2022).
NLE1 also shares sentences with these, for which no sentence is quoted: Neurological Disease (1 paper).